AURKA (aurora kinase A)
Diseases named in the same sentence as AURKA in open-access papers (continued):
Sharing a sentence is not in itself a finding about the gene and the disease.
lung carcinoma (continued). "Moreover, AURKA mRNA was significantly over-expressed in poor (grade III) or moderately differentiated (grade II) lung cancer specimens compared to well-differentiated cases (grade I) (p < 0.01)." (PMID 21718475, 2011). "To test the hypothesis of a similar mechanism in lung cancer we evaluated the effect of AURKA inhibition in non small carcinoma cell lines (H522, H1299 and Calu1)." (PMID 21718475, 2011). "Moreover, AURKA was principally up-modulated in moderately and poorly differentiated lung cancers (p < 0.01), as well as in squamous and adenocarcinomas compared to the non-invasive bronchioloalveolar histotype (p = 0.029)." (PMID 21718475, 2011). "Therefore, it is possible that like ES, in lung cancer, AURKA may stabilize YAP1 indirectly by phosphorylating NPM1." (PMID 39334449, 2024). "Moreover, because AURKA can enhance the resistance of lung cancer to third-generation EGFR inhibitors, a dual effect of AURKA SNPs and EGFR mutations on the clinicopathological characteristics of LADC may occur, thus requiring evaluation." (PMID 33050100, 2020). "Therefore, we hypothesized that the inhibition of AURKA with MLN8237 will decrease survival in lung cancer cell lines and increase sensitivity to irradiation." (PMID 31647033, 2019). "Here, we demonstrate that knocking down AURKA in a doxycycline-inducible system or inhibiting AURKA by MLN8237 improves cisplatin and radiation activity in multiple lung cancer cell lines and in an in vivo xenograft model." (PMID 39199578, 2024). "Clinical trials in progress are assessing potential combination activity of the AURKA inhibitor alisertib with the EGFR inhibitor osimertinib (e.g., NCT04085315) in metastatic EGFR-mutant lung cancer." (PMID 38639476, 2024). "In contrast, other studies using alternative sample sources and methods of analysis found AURKA SLR increased in cancer samples, specifically in breast and lung cancers, where such increase even correlated with poor prognosis and survival." (PMID 39527514, 2024). "qRT-PCR confirmed that the expression level of CDKN3, MKI67, CEP55, SPAG5, AURKA, TOP2A were highly expressed in lung cancer tissues." (PMID 35178291, 2022). "We screened mitotic kinase small molecule inhibitors against PLK1 (volasertib), Aurora kinase A (alisertib), and CHK1 inhibitor (AZD7762) in human and mouse lung cancer cell lines." (PMID 35871223, 2022). "AURKA siRNA and small molecule AURKA inhibitors, including ENMD-2076, Aurora A inhibitor I, and alisertib, induced selective toxicity in RB1−/− lung cancer cells." (PMID 34050264, 2021). "Supporting a requirement for RIT1, AURKA, IGF1R, and FURIN in the proliferation of RIT1-mutant lung cancer, knockout of each gene significantly reduced cell proliferation of H2110iCas9 compared to cells expressing a non-targeting control guide (sgNTC)." (PMID 34373451, 2021). "Comparative analysis of p-AURKA/AURKA between normal samples and all cancer tumors indicated a 3.43-fold and 3.12-fold enhancement of protein level in the CRC group and lung cancer group, respectively (P < 0.001)." (PMID 32469983, 2020). "Osimertinib and rociletinib, two anti-cancer drugs for lung cancer, work by shutting off mutant EGFR, which initially kills cancerous tumors, but the tumors rewire and activate Aurora kinase A, becoming cancerous growths again." (PMID 32795325, 2020). "On the other hand, analysis of the p-AURKA/AURKA ratio between early and advanced tumor stages of CRC and lung cancer groups resulted in a 1.88-fold increment (P < 0.001), and 1.14-fold elevation (P = 0.021) of p-AURKA/AURKA ratio, respectively." (PMID 32469983, 2020). "The Kaplan–Meier survival analysis was performed to plot the OS of colon and lung cancer patients with abnormal levels of CALU, AURKA, and MCM2, in separate form and as a panel." (PMID 32469983, 2020).
lung carcinoma (continued). "These authors demonstrated that using the dual AURKA and AURKB inhibitor, AI II, reduces growth, viability, and anchorage-independent growth in a KRAS-dependent manner, showing that AURKA and AURKB are promising targets for KRAS-induced lung cancer therapy." (PMID 33202573, 2020). "Meanwhile, AURKA not only played a crucial role in the collective invasion in MDA-MB-231 cells, but also in the A549 cells (lung cancer cell line) and AGS cells (gastric cancer cell line)." (PMID 28592839, 2017). "It was previously shown that in A549 human lung cancer cells, FTS treatment decreases AURKA mRNA levels, and inhibits its assembly at the spindle poles." (PMID 28151959, 2017). "In this work we demonstrated that AURKA and AURKB are potential new promising targets for KRAS-induced lung cancer therapy." (PMID 26842935, 2016). "EGFR-Thr654 and EGFR-Ser1046 phosphorylation decreased upon application of an AURKA inhibitor, but only in EGFR-L858R mutant cell lines, which raised the possibility of the therapeutic application of AURKA inhibitors in lung cancer patients." (PMID 23520446, 2013). "We have previously shown by microarray analysis of primary lung carcinomas and matched normal tissue that AURKB (22 out of 37) and AURKA (15 out of 37) transcripts are frequently over-represented in these tumours." (PMID 16222316, 2005). "Further intersecting these predicted targets with transcriptomic datasets from breast, colorectal, and lung cancers highlighted hub proteins such as TYMS, AURKA, CDK1, and TK-1, which are critical regulators of DNA synthesis, mitotic progression, and cell cycle checkpoints." (PMID 40430485, 2025). "In addition, AURKA knockdown improved the sensitivities of PC9 and A549 lung cancer cells to cisplatin in a synergistic manner in cell viability and colony formation assays (CI ˂ 1)." (PMID 39199578, 2024). "Lung cancer patients’ prognoses are often foreseen using matched prognostic models, and genes CENPF, AURKA, PBK, and CCNB1 in lung cancer may serve as therapeutic targets, which require further investigations." (PMID 36984548, 2023). "Consistently, AURKA expression in lung cancer cell lines was significantly higher than that in non-transformed HBE cells, and showed stronger nuclear localization characteristics." (PMID 35361747, 2022). "We analyzed the expression of aurora kinase A and discovered a negative correlation between expression levels and OS rates in patients with lung cancer and adenocarcinoma (a major representative form of NSCLC)." (PMID 35745617, 2022). "Here, we unveil that non-canonical activation of nuclear AURKA promotes an oncogenic RNA splicing of tumor suppressor RBM4 directed by m6A reader YTHDC1 in lung cancer." (PMID 35361747, 2022). "For example, the combination of osimertinib and alisertinib, an aurora kinase A inhibitor, was used in a phase I clinal trail of EGFR-mutant lung cancer, and a randomized phase III clinical trial of alisertinib was performed for relapsed or refractory peripheral T-cell lymphoma." (PMID 35745617, 2022). "Moreover, patients with lung cancer and NSCLC exhibiting higher expression of aurora kinase A demonstrated relatively lower OS rates." (PMID 35745617, 2022). "Moreover, up-regulation of AURKA/PLK/CDK1 contributes to PI3K inhibitor resistance in glioblastoma, and AURKA drives the evolution of resistance to EGFR inhibitor in lung cancer." (PMID 34359608, 2021). "Similar to AURKA, upregulated levels of AURKB in lung cancer have also been associated with negative prognosis and poor therapeutic response." (PMID 33202573, 2020). "The Aurora kinases, Aurora-A (AURKA), and Aurora B (AURKB) are overexpressed in many tumor entities such as lung cancer that correlate with poor survival, whereby their inhibition, in most cases, enhances the efficacy of chemo-and radiotherapies, indicating their implication in cancer therapy." (PMID 33202573, 2020).
lung carcinoma (continued). "In order to validate AURKA and/or AURKB as therapeutically relevant KRAS targets in lung cancer, we treated A549 and H358 cells, as well as two different lung cell based models of gain-of-function of KRAS with a dual Aurora kinase inhibitor and performed functional in vitro assays." (PMID 26842935, 2016). "However, the relationship of AURKA, EGFR-WT, and mutant EGFR must be further evaluated to identify therapeutic targets for lung cancer patients." (PMID 23520446, 2013). "We report that AURKA expression/activity in lung cancer cell lines does not regulate the transcriptional level of E-Cadherin." (PMID 21718475, 2011). "Given that canonical metabolic drugs may also harm normal cells, the combination of AURKA inhibitors with L-asparaginase, as reported in a recent study for KEAP1 mutant lung cancer, holds promise for achieving enhanced therapeutic efficacy and merits further investigation." (PMID 38521813, 2024). "Expression of aurora A kinase is correlated with cisplatin resistance in NSCLC: in vitro data of 102 NSCLC patients treated with surgery and adjuvant cisplatin-based chemotherapy showed that AURKA expression was elevated in cisplatin-resistant lung cancer cells." (PMID 36387232, 2022). "Moreover, AURKA overexpression in TNBC identifies as a factor of early recurrence and poor prognosis and AURKA showed 3′UTR shortening in poor-prognosis patients of both breast and lung cancer." (PMID 36067794, 2022). "Finally, Aurora kinase pharmacological inhibition preferentially targets lung cancer cells expressing KRASG12V, thereby supporting our hypothesis that AURKA and AURKB are promising targets for KRAS-induced lung cancer therapy." (PMID 26842935, 2016). "These authors further showed that although AURKA does not regulate the nucleo/cytoplasmic spread of YAP, it increases its protein levels and transcriptional activity in lung cancer cells using its kinase activity." (PMID 39334449, 2024).
ovarian carcinoma (67 papers, 2003 to 2026). A malignant neoplasm originating from the surface ovarian epithelium. "Overexpression of AURKA has been reported particularly in colorectal adenocarcinoma, non-small cell lung cancer, and ovarian cancer, and has been associated with poor prognosis and treatment resistance." (PMID 41515655, 2026). "In earlier work, it has been observed that the amplification of AURKA was associated with sensitivity to PARP inhibitors in 39 ovarian cancer cell lines, indicating an underlying mechanistic link between the AURK and PARP pathways." (PMID 38177929, 2024). "Several studies have shown that AURKA is frequently amplified in several tumors, including breast, pancreatic, colorectal, gastric, and ovarian carcinomas, and in some cases is associated with a poor prognosis." (PMID 33824269, 2021). "Next, we tried to investigate the biological mechanisms underlying associations between the DNA methylation sites and ovarian cancer with AURKA." (PMID 30944378, 2019). "To understand the effects of AURKA inhibition, in the context of HR-proficiency and HR-deficiency, we employed a large panel of established ovarian carcinoma cell lines, including PEO1, SKOV3ip2, PEO4, OVCA429, MDAH, A2780, OVCAR5 and OVCAR10." (PMID 28881569, 2017). "Aberrant amplification of AURKA occurs in human malignancies such as breast, pancreatic, colorectal, gastric, and ovarian carcinomas and in some cases is associated with a poor prognosis." (PMID 25625960, 2015). "Overexpression of AURKA is independently associated with chromosomal instability in colorectal cancer, and AURKA expression has a prognostic value in ovarian carcinoma." (PMID 22920630, 2012). "Even if the molecular mechanism of AURKA is complex, several researches implied that AURKA protein expression is strongly linked with poor patient outcome and aggressive disease characteristics of ovarian cancer." (PMID 28187748, 2017). "Abnormal expression of AURKA has been observed in breast, colorectal, gastric, pancreatic, lung, and ovarian cancers." (PMID 40564876, 2025). "In ovarian cancer, AURKA regulates the p16 pathway through the SOX8-FOXK1 signaling axis, inhibiting cellular senescence and enhancing glucose metabolism, ultimately leading to cisplatin resistance." (PMID 39135779, 2024). "CHEK1 inhibition with LY2603618 is synthetic lethal in combination with alisertib, an AURKA inhibitor, in ovarian cancer cells by sensitizing them to platinum and inducing apoptosis." (PMID 36011043, 2022). "AURKA inhibition is also synthetic lethal ARID1A-deficient colorectal cancer cells and with CHEK1 kinase inhibitors in ovarian cancer." (PMID 36011043, 2022). "Aurora kinase A (AURKA) was also included since it was recently shown to modulate epithelial ovarian cancer cell adhesion and migration, in turn, promoting cancer cell dissemination." (PMID 33747961, 2021). "AURKA is abundantly expressed in a variety of cancer types and plays an important role in the proliferation of ovarian cancer cells." (PMID 34616431, 2021). "Alisertib is the most extensively studied AURKA inhibitor in a wide range of tumor types, including lymphoma, small cell lung cancer, ovarian cancer, leukemia, gliomas, and myeloma." (PMID 34050264, 2021). "Among all the investigated genes, AURKA and MAL expression levels showed the best correlation with progression free survival (PFS) and the overall survival (OS) of ovarian cancer patients, and high expression levels were associated with a poor prognosis." (PMID 31336942, 2019). "AURKA has been highly expressed in various malignant tumors, such as esophageal cancer, laryngeal cancer, liver cancer, and ovarian cancer." (PMID 30995921, 2019). "High expression of AURKA is found frequently in several human malignancies, including breast and ovarian cancer." (PMID 30104527, 2018).
ovarian carcinoma (continued). "Since AURKA is essential for ovarian carcinoma cell survival, highly efficient AURKA knockdown is lethal to cells." (PMID 28881569, 2017). "We and others have reported amplification and overexpression of AURKA in several malignancies including gastric, esophageal, colon, breast, and ovarian cancers." (PMID 28417568, 2017). "In the current study, we investigated the role of AURKA in regulating the DNA damage response and DNA repair in ovarian carcinoma cells." (PMID 28881569, 2017). "First, AURKA inhibition induces the formation of pH2AXS139 foci (i) in the nucleus, similar to the effects of PARPi on ovarian carcinoma cells." (PMID 28881569, 2017). "In contrast to these findings for PARPi, we discovered that inhibition of AURKA activity with alisertib significantly diminished the growth and clonogenic survival of PARPi-sensitive and -resistant ovarian carcinoma cells." (PMID 28881569, 2017). "Aurora A kinase (AURKA) plays an important role in ovarian cancer progression by mediating mitosis and chromosomal instability." (PMID 28881569, 2017). "Role of NEK2, CCNA2, and AURKA as potential targets in ovarian cancer has been recently highlighted by a detailed systematic bioinformatic study." (PMID 26992853, 2016). "High levels of AURKA expression is closely correlated to poor survival of patients with ovarian cancer." (PMID 26317392, 2015). "In ovarian cancer that is a poor prognostic gynecological cancer, AURKA overexpression is also found in cell lines and cancer tissues and is associated with poor prognosis in cancer patients." (PMID 25625960, 2015). "Recent reports showed the potential efficacy of combining AURKA inhibitor with taxanes in epithelial ovarian cancer." (PMID 25625960, 2015). "Many of the genes from this set that are highly expressed in CEPI promote entry into and progression through the cell cycle (e.g., FOXM1, PTTG1, AURKA) and have been previously associated with stage III epithelial ovarian cancers." (PMID 20040092, 2009). "Based on these results, we believe that targeting AURKA could be a new alternative therapy for HGSOC, especially since AURKA is often amplified in ovarian cancer." (PMID 39851561, 2025). "Additionally, compared with normal ovarian tissues, ovarian cancer tissues exhibited significantly higher AURKA transcript levels (p < 0.001)." (PMID 36601056, 2022). "Furthermore, blockade of AURKA in preclinical models of ovarian carcinoma leads to decreased proliferation and increased apoptosis." (PMID 35059393, 2021). "Since AURKA and MAL have been implicated in ovarian cancer pathology and are, therefore, functionally important rather than the outcome of a deregulation side effect, they are promising nominees to include in a panel of novel biomarkers for the detection of ovarian cancer." (PMID 31336942, 2019). "AURKA plays an significant role in ovarian cancer cell proliferation." (PMID 30944378, 2019). "Meanwhile, in the analysis of ovarian cancer data from TCGA, NAMDD found 389 significant path associations, among which, we investigated and explained the disease pathogenesis mechanisms, including the CCNE1, AURKA, and RAB25 genes." (PMID 30944378, 2019). "Given the success of PARPis for the treatment of OC, particularly HR-deficient cancers, we explored the potential connection of AURKA activation on cell growth, the DDR and DNA repair in PARPi-sensitive (HR-deficient) and PARPi-resistant (HR-proficient) ovarian carcinoma cells." (PMID 28881569, 2017). "Inhibition of AURKA activity also decreased the expression of BRCA1/2 in ovarian carcinoma cells." (PMID 28881569, 2017). "To determine the effects of inhibiting AURKA activity on the DDR in ovarian carcinoma cells, we first analyzed the effect of alisertib treatment on the expression of important HR and NHEJ pathway signaling molecules, in PARPi-sensitive (PEO1) and -resistant (PEO4 and SKOV3ip2) cell lines." (PMID 28881569, 2017).